SERPINA5 (serpin family A member 5)
Description:
Heparin-dependent serine protease inhibitor acting in body fluids and secretions. Inactivates serine proteases by binding irreversibly to their serine activation site. Involved in the regulation of intravascular and extravascular proteolytic activities. Plays hemostatic roles in the blood plasma. Acts as a procoagulant and pro-inflammatory factor by inhibiting the anticoagulant activated protein C factor as well as the generation of activated protein C factor by the thrombin/thrombomodulin complex. Acts as an anticoagulant factor by inhibiting blood coagulation factors like prothrombin, factor XI, factor Xa, plasma kallikrein and fibrinolytic enzymes such as tissue- and urinary-type plasminogen activators. In seminal plasma, inactivates several serine proteases implicated in the reproductive system. Inhibits the serpin acrosin; indirectly protects component of the male genital tract from being degraded by excessive released acrosin. Inhibits tissue- and urinary-type plasminogen activator, prostate-specific antigen and kallikrein activities; has a control on the sperm motility and fertilization. Inhibits the activated protein C-catalyzed degradation of SEMG1 and SEMG2; regulates the degradation of semenogelin during the process of transfer of spermatozoa from the male reproductive tract into the female tract. In urine, inhibits urinary-type plasminogen activator and kallikrein activities. Inactivates membrane-anchored serine proteases activities such as MPRSS7 and TMPRSS11E. Inhibits urinary-type plasminogen activator-dependent tumor cell invasion and metastasis. May also play a non-inhibitory role in seminal plasma and urine as a hydrophobic hormone carrier by its binding to retinoic acid.
Synonyms: PAI-3; PAI3; PCI; PLANH3; PROCI; PCI-B
Tractability: Small molecule: it has a high-quality binding pocket. Antibody: UniProt places it where antibodies can reach, with high confidence; its Gene Ontology location is reachable by antibodies, with high confidence; UniProt predicts a signal peptide or a membrane-spanning region. PROTAC: its protein half-life has been measured.
Safety:
Unwanted effects reported when the protein is acted on. In parentheses: how it was acted on, where the effect was seen, and who reports it.
thrombocytopenia (source: ClinPGx)
Gene: Protein-coding gene on chromosome 14 (94,561,442 to 94,593,120, forward strand). Ensembl gene ENSG00000188488.
Subcellular location: Secreted, extracellular space
Pathways (Reactome):
Hemostasis: Amplification and propagation of coagulation cascade; Fibrin formation; Regulation of clotting cascade
Gene Ontology:
Molecular function: acrosin binding; phosphatidylcholine binding; protease binding; protein binding; retinoic acid binding; serine-type endopeptidase inhibitor activity; glycosaminoglycan binding; heparin binding
Biological process: seminal clot liquefaction; fusion of sperm to egg plasma membrane involved in single fertilization; spermatogenesis
Cellular component: acrosomal membrane; external side of plasma membrane; extracellular exosome; extracellular matrix; extracellular region; membrane; platelet alpha granule; platelet dense tubular network; protein C inhibitor-coagulation factor V complex; protein C inhibitor-coagulation factor Xa complex; protein C inhibitor-coagulation factor XI complex; protein C inhibitor-KLK3 complex; protein C inhibitor-plasma kallikrein complex; protein C inhibitor-PLAT complex; protein C inhibitor-PLAU complex; protein C inhibitor-thrombin complex; protein C inhibitor-TMPRSS11E complex; protein C inhibitor-TMPRSS7 complex; protein-containing complex
Genetic constraint (gnomAD): Loss-of-function variants: 25 observed, 26.45 expected, observed/expected ratio (o/e) 0.95, 90% interval 0.69 to 1.32. The upper end of that interval is the gene's LOEUF score, 1.32, which puts it in group 5 of 6, group 1 being the genes least tolerant of losing a copy. Missense variants: 599 observed, 535.21 expected, observed/expected ratio (o/e) 1.12, 90% interval 1.05 to 1.2. Synonymous variants: 234 observed, 217.68 expected, observed/expected ratio (o/e) 1.08, 90% interval 0.96 to 1.2.
Homologues: Orthologues: chimpanzee SERPINA5 (99% identical), macaque SERPINA5 (84% identical), pig SERPINA5 (76% identical), dog SERPINA5 (73% identical), mouse Serpina5 (63% identical), rat Serpina5 (63% identical), guinea pig SERPINA5 (57% identical). Paralogues in human: SERPINA3 (46% identical), SERPINA4 (44% identical), SERPINA9 (44% identical), SERPINA1 (42% identical), SERPINA6 (41% identical), SERPINA11 (39% identical), SERPINA7 (37% identical), SERPINA12 (35% identical), SERPINB1 (32% identical), SERPINB9 (32% identical), SERPINA10 (31% identical), SERPINB10 (31% identical), and 24 more.
Diseases named in the same sentence as SERPINA5 in open-access papers:
SERPINA5 is named in the same sentence as 78 diseases in open-access papers, as found by Europe PMC text mining. Sharing a sentence is not in itself a finding about the gene and the disease. The quoted sentences say what the papers report.
breast carcinoma (9 papers, 2005 to 2025). "SERPINA5 suppresses breast cancer cell proliferation, metastasis, angiogenesis, and cell invasion by decreasing urokinase (uPA) and enhancing breast cancer cell adhesion." (PMID 38136662, 2023). "In breast cancer, overexpression of SERPINA5 inhibits tumour metastasis potential and lowly expressed SERPINA5 inhibits cell migration in hepatocellular carcinoma." (PMID 36000536, 2022). "SERPINA5 expression is decreased in renal and prostate cancer and elevated levels have been related to better survival in breast cancer." (PMID 23268721, 2012). "Similarly, overexpression of SERPINA5 resulted in decreased invasion and angiogenesis in breast cancer." (PMID 40698088, 2025). "In addition, the increased SERPINA5 protein expression is correlated with a prolonging in the survival time of patients with primary breast cancer." (PMID 36000536, 2022). "Recent publications regarding diverse medical conditions, including pediatric leukemia, breast cancer, HIV infection, and hepatocellular carcinoma have identified the role of SERPINA5." (PMID 27193112, 2016).
COVID-19 (8 papers, 2020 to 2025). A disease caused by infection with severe acute respiratory syndrome coronavirus 2. "Of note, the latest study demonstrated that the rs2093266 and rs1955656 polymorphisms in SerpinA4 and SerpinA5 genes might be risk factors for COVID-19-induced AKI (acute kidney injury)." (PMID 36982532, 2023). "According to these criteria, we found four procoagulants (ADAMTS13, F11, HGFAC, KLKB1) and two anticoagulants (C1QTNF1, SERPINA5), whose expression may predispose males and older individuals to COVID-19-related coagulopathy and severe COVID-19 disease." (PMID 32751741, 2020). "SERPINA5 and leptin showed the greatest downregulation as COVID-19 severity increased." (PMID 33704068, 2021). "Several key factors in the coagulation pathway, including F5, F12, and SERPINA5, were also elevated in PLWH with COVID-19." (PMID 40568587, 2025). "Conversely, components of the coagulation cascade (SERPINA5, SERPIND1, PROC, CPB2, F13B, and KLKB1) and proteins involved in cholesterol metabolism were downregulated with the severity of COVID-19 but increased over time." (PMID 35958562, 2022). "In our results, F11, F9, FGG, FGA, SERPINA5, SERPINC1, and SERPINF2 are involved in the coagulation cascade, and significantly higher expressed in COVID-19-children compared with COVID-19-adults." (PMID 34335977, 2021). "On the contrary, we found a number of plasma serine protease inhibitors such as SERPINA5, SERPINC1, and SERPINF2, which negatively regulate the blood coagulation cascade 29, were strongly up-regulated in COVID-19-children against in healthy children or COVID-19-adults." (PMID 34335977, 2021).
acute kidney injury (4 papers, 2017 to 2024). Sudden and sustained deterioration of the kidney function characterized by decreased glomerular filtration rate, increased serum creatinine or oliguria. "SERPINA4 and SERPINA5, but not BCL2 and SIK3 are associated with acute kidney injury in critically ill patients with septic shock." (PMID 35874763, 2022).
hepatocellular carcinoma (4 papers, 2016 to 2024). A malignant tumor that arises from hepatocytes. "Previous studies indicated that the dysregulation of SERPINA5 has been implicated in migration, invasion and metastasis in hepatocellular carcinoma, ovarian and prostate cancers." (PMID 32547876, 2020). "SERPINA5 is a versatile protein that is downregulated in breast, ovarian, and hepatocellular carcinomas." (PMID 39012409, 2024).
Infertility (4 papers, 2017 to 2022). "Deficiency of SERPINA5 results in a defective spermatogenesis process and is a cause of infertility." (PMID 31336797, 2019). "Furthermore, validation of SERPINA5 in spermatozoa signifies this protein as a candidate marker for identifying the cause of infertility in normozoospermic infertile men." (PMID 31336797, 2019). "Therefore, SERPINA5 protein underexpression in normozoospermic infertile men compared to fertile men provides an insight into its role in infertile men with normal semen parameters." (PMID 31336797, 2019). "Of the four validated proteins, SPA17 and SERPINA5 were underexpressed and ANXA2 was overexpressed (p < 0.05) in UMI subjects, whereas the expression level of PRDX2 was comparable for normozoospermic fertile and infertile men." (PMID 31336797, 2019).
glioma (3 papers, 2020 to 2021). A benign or malignant brain and spinal cord tumor that arises from glial cells (astrocytes, oligodendrocytes, ependymal cells). "While the exact role of SERPINA5 in glioma progression remains to be determined." (PMID 32547876, 2020). "High DEGs in grade II gliomas included NNMT, MFAP5, APCDD1L-AS1, C7orf57, HP, SERPINA5, and LTF and some highly downregulated DEGs included ABCA4, PDE6A, GRP, RD3, and TMEM72." (PMID 33948562, 2021). "Additionally, SERPINA5 and TIMP1 mRNA expression were significantly increased with the increase of glioma grades in both TCGA LGG dataset and CGGA dataset." (PMID 32547876, 2020).
ovarian carcinoma (3 papers, 2013 to 2020). A malignant neoplasm originating from the surface ovarian epithelium. "SERPINA5 was reported to be deregulated in renal, breast, prostate, liver, and ovarian cancers and have a protective role against tumor development, invasiveness, and metastasis." (PMID 30941304, 2019). "SERPINA5 expression was shown to be downregulated in ovarian cancer (OC)." (PMID 32228439, 2020).
preeclampsia (3 papers, 2021 to 2023). Preeclampsia is a hypertensive disorder of pregnancy that is characterized by new-onset hypertension with proteinuria presenting after 20 weeks of gestation, and depending on mild or severe forms may initially present with severe headache, visual disturbances, and hyperreflexia. "We further found that placenta-derived plasma SerpinA5 together with uterine artery Doppler ultrasound and clinical risk factor can more effectively predict preeclampsia." (PMID 34648566, 2021). "This study aimed to combine plasma protein SerpinA5 with uterine artery doppler ultrasound and clinical risk factor during the first trimester for prediction of preeclampsia." (PMID 34648566, 2021). "In summary, SerpinA5 may be a novel biomarker for preeclampsia and SerpinA5 in conjunction with uterine artery pulsatility index and clinical risk factor may be helpful for the early prediction of preeclampsia." (PMID 34648566, 2021). "SerpinA5 has pathological roles in the invasion of trophoblast cells, which is related to the pathological features of preeclampsia." (PMID 34648566, 2021). "In the developing set, we demonstrated higher SerpinA5 levels in plasma of preeclampsia than in the control via ELISA (0.293 ±0.266 ng/ml vs. 0.074±0.033 ng/ml, P<0.001) (n = 48:48)." (PMID 34648566, 2021). "What is more, the sensitivity and specificity of predictive power were strengthened when plasma SerpinA5 was combined with UtA-PI and pre-pregnancy BMI & family history of PE for prediction of preeclampsia." (PMID 34648566, 2021). "We also demonstrated that the staining of SerpinA5 (average optical density (IOD [mean]) in preeclampsia placental tissue was greater than that in the control (P<0.05)." (PMID 34648566, 2021). "In this study, we further demonstrated that SerpinA5 levels were greater not only in preeclampsia placental tissue but also in PE gravidas’ plasma than levels in the control (P<0.05)." (PMID 34648566, 2021). "We demonstrated that SerpinA5 levels were greater not only in preeclampsia placental tissue but also in plasma (both p<0.05), and we found that SerpinA5 may interfere with trophoblastic cell invasion by inhibiting MSP." (PMID 34648566, 2021). "In the current study, we studied the relationship between SerpinA5 and preeclampsia and whether SerpinA5 can be used as a potential biomarker for preeclampsia, and a multi-element prediction model for preeclampsia was established." (PMID 34648566, 2021). "The overexpression of SERPINA5 exacerbates L-NAME-induced proteinuria, gestational hypertension, and unfavorable pregnancy outcomes such as fetal growth restriction and miscarriage." (PMID 38136662, 2023).
prostate carcinoma (3 papers, 2012 to 2022). A carcinoma that arises from epithelial cells of the prostate gland. "Pervious study demonstrated that loss of the expression of SERPINA5 is correlated with high‐grade tumours on prostate cancer." (PMID 36000536, 2022).
sarcopenia (3 papers, 2023 to 2025). Progressive decline in muscle mass due to aging which results in decreased functional capacity of muscles. "Among them, MYH8, HOXB2, C1QA, CDKN1A, and SLC38A1 are associated with sarcopenia, and in this study, LGR5, SERPINA5, and TPPP3 genes were found to be associated with Sarcopenia for the first time." (PMID 38229116, 2024). "Consistent with the literature, we found that PAX5 and SERPINA5 were positively correlated with muscle function and that their expression levels were significantly reduced in sarcopenia." (PMID 37525094, 2023). "In patients with sarcopenia, the expression of TPPP3, C1QA, LGR5, MYH8, and CDKN1A genes are upregulated, and the expression of SLC38A1, SERPINA5, and HOXB2 genes are downregulated." (PMID 38229116, 2024).
Sepsis (3 papers, 2017 to 2024). Sepsis is defined as life-threatening organ dysfunction caused by a dysregulated host response to infection. "SERPINA5 limits the activity of the anticoagulant protein C. It acts as an anti-inflammatory factor in severe inflammatory disorders, such as sepsis." (PMID 38715599, 2024).
Alzheimer disease (2 papers, 2022). A progressive, neurodegenerative disease characterized by loss of function and death of nerve cells in several areas of the brain leading to loss of cognitive function such as memory and language. "It is reported that SERPINA5 was associated with Alzheimer’s disease (AD) and Parkinson’s disease (PD)." (PMID 36699448, 2022).
coronary heart disease (2 papers, 2020 to 2022). "Other proteins associated with incident HF in our research have been linked to coronary heart disease (ANG, C1QTNF1 and CCL3) and thromboembolism (SERPINA5) with the potential to induce myocardial damage." (PMID 35945262, 2022).
endometrial cancer (2 papers, 2025). Primary or metastatic malignant neoplasm involving the endometrium (mucous membrane that lines the endometrial cavity). "The delivery of SERPINA5 through exogenous exosomes decreased the migratory potential of endometrial cancer cells." (PMID 40698088, 2025). "SERPINA5 (serpin family A member 5) was discovered and subsequently validated in an independent cohort to be elevated in endometrial cancer cases versus controls in two studies by the same authors (AUC = 0.77)." (PMID 40987065, 2025).
heart failure (2 papers, 2018 to 2023). Inability of the heart to pump blood at an adequate rate to meet tissue metabolic requirements. "In addition, aberrantly expressed SERPINA5 contributed to heart failure and osteoarthritis in the elderly." (PMID 37525094, 2023).
hepatic cancer (2 papers, 2020 to 2024). "Plasma serine protease inhibitor (SERPINA5), mainly synthesized in the liver, is a multifunctional tumor suppressor that reduces the metastatic property of hepatic cancer cell lines by disrupting the fibronectin–integrin signaling pathway." (PMID 32845921, 2020).
Hypertension (2 papers, 2017 to 2023). The presence of chronic increased pressure in the systemic arterial system. "Our findings suggest that the pre-inhibition of SERPINA5 expression partially alleviates PE-like features in rats, as evidenced by reduced hypertension, proteinuria, and improved placental development." (PMID 38136662, 2023). "On the other hand, L-NAME-induced hypertension and proteinuria were somewhat alleviated, and fetal growth was recovered in rats by preemptively suppressing SERPINA5 expression." (PMID 38136662, 2023). "The overexpression of SERPINA5 exacerbated L-NAME-induced hypertension and proteinuria in pregnant rats." (PMID 38136662, 2023). "L-NAME-induced hypertension and proteinuria were mitigated when SERPINA5 expression was suppressed." (PMID 38136662, 2023). "This proteoglycan binds to and modulates the effects of several proteins, including heparin-dependent serine protease inhibitors such as antithrombin III (AT3, SerpinC1) and protein C inhibitor (PCI, PAI-3, SerpinA5), both of which we found increased in urinary exosomes of hypertensive patients." (PMID 28562335, 2017).
melanoma (2 papers, 2020 to 2022). A malignant, usually aggressive tumor composed of atypical, neoplastic melanocytes. "In additional, researchers demonstrated that host SERPINA5 inhibit tumour growth, but promote tumour metastasis in B16 melanoma." (PMID 36000536, 2022). "In addition, another study showed that SERPINA5 inhibits tumour growth and promotes tumour metastasis in B16 melanoma." (PMID 36000536, 2022).
metastatic cancer (2 papers, 2021 to 2024). A carcinoma which has spread from the original site of growth to another anatomic site. "We also observed CDH2, CP, HP, TF, and SERPINA5 were upregulated in liver metastatic cancer tissues and downregulated in primary cancer tissues; whereas SPARCL1 exhibited the opposite expression pattern." (PMID 34422629, 2021). "Therefore, in the observed tissues, SPARCL1 was most highly expressed in normal colorectal tissues, and CDH2 had the highest expression in normal liver tissues and liver metastatic cancer tissues, while CP, HP, TF, and SERPINA5 with the most highly expressed in normal liver tissues." (PMID 34422629, 2021).
ovarian serous carcinoma (2 papers, 2012 to 2025). "Reduction in SERPINA5 expression was linked with an aggressive tumor phenotype and poor prognosis in endometrial and ovarian serous carcinomas." (PMID 40698088, 2025). "Decreased SERPINA5 expression was correlated with downstream activation of MMP9 in ovarian serous carcinomas." (PMID 40698088, 2025). "Gene and protein expression analysis revealed SERPINA5, the gene encoding PCI, as down-regulated in serous ovarian carcinomas compared with serous borderline tumors, which is consistent with our MS results." (PMID 23268721, 2012).
papillary thyroid cancer (2 papers, 2021 to 2022). "SERPINA5 has recently been proposed as a novel susceptibility locus for papillary thyroid cancer, with SERPINA5 having a significantly prognostic value in colorectal cancer." (PMID 36000536, 2022). "A few researches evaluated the association of polymorphisms at SERPINA5 and fat mass and obesity-associated protein (FTO) genes with papillary thyroid cancer (PTC) globally." (PMID 34837923, 2021).
schizophrenia (2 papers, 2014 to 2025). A major psychotic disorder characterized by abnormalities in the perception or expression of reality. "Both SERPINA5 and CNDP1 have been linked to schizophrenia as have other serine protease inhibitors." (PMID 39911945, 2025).